TNF (tumor necrosis factor)
Diseases named in the same sentence as TNF in open-access papers (continued):
Sharing a sentence is not in itself a finding about the gene and the disease.
tumor (continued). "Another pair TNF_TNFRSF1B could activate the nuclear factor κB pathway and resisted TNF-induced tumor cell death." (PMID 34805166, 2021). "Moreover, given the pro-inflammatory subtype, IL-12-dependent macrophages can directly kill tumor cells via TNF-α secretion." (PMID 34394072, 2021). "For example, platelet-derived growth factor DD (PDGF-DD) has been shown to be released by many types of tumors and to activate the NK cells’ receptor NKp44, stimulating the secretion of interferon-γ (IFN-γ), tumor necrosis factor-α (TNF-α) and chemokines to trigger tumor cell–cycle arrest." (PMID 33530529, 2021). "Importantly, two-way ANOVA demonstrated a significant interaction between DOX administration and the tumor on the serum levels of IL-6 and TNF-α." (PMID 34445729, 2021). "Additionally, MSC-sourced TNF-α induces the necrosis of tumor cells and enhances the expression of E and P selectins on tumor endothelial cells, enabling a massive influx of immune cells." (PMID 34830312, 2021). "Similarly, IFN-γ and TNF-α production were decreased in CD103+ tumor-infiltrating T cells compared with other T cell subsets in head and neck squamous cell carcinoma." (PMID 34571883, 2021). "Notably, the levels of CD3+CD8+IFN-γ+ T cells and CD3+CD8+TNF-α+ T cells in tumor were significantly elevated by Oxa(IV)@ZnPc@M (+) + anti-PD-L1 treatment." (PMID 34262026, 2021). "Nuclear factor kappa beta and STAT3 hyperactivation in tumor cells and immune cells in the tumor microenvironment in turn promotes production of several pro-inflammatory cytokines including IL-1β, IL-6, and TNFα, which promote survival and proliferation of tumor cells." (PMID 35048057, 2021). "PDGF-DD stimulation of NKp44 induced NK cell secretion of IFN-γ and TNF that arrest tumor cell proliferation in vitro and may confer a survival benefit in GBM." (PMID 34539622, 2021). "In mice, the combination of lenalidomide and elotuzumab was very effective in reducing tumor volume and increasing the infiltration of NK cells into the tumor microenvironment, an effect enhanced by IL-2 secreted by T cells and TNF-alpha produced by monocytes and macrophages." (PMID 34307150, 2021). "Although anti-tumor functions were described for TNFα when it was administered locally at high doses to patients and cancer-bearing animals, the chronic presence of TNFα in tumors during their progression was strongly connected to a more aggressive disease phenotype in many tumor types." (PMID 34201054, 2021). "Besides affecting anti-cancer immunity, TNFα and TGFβ signaling also have direct tumor-suppressing or oncogenic effects on tumor cells." (PMID 33767579, 2021). "Through the experimental results, the authors speculated that neutrophils and TNF‐α were involved in the anti‐tumor process." (PMID 33854892, 2021). "We found Y111, but not CD3 Isotype or PD-L1 mAb could significantly enhance the secretions of IFNγ, TNFα, and granzyme B from the expanded Vγ2Vδ2 T cells in the presence of tumor cells." (PMID 34040604, 2021). "Moreover, the cytotoxicity assay also proved that blocking Ogr1 impelled T cells to migrate to the tumor’s boundary, and killed tumor cells by secreting sufficient granzyme B, TNF, and an appropriate amount of IFN-γ." (PMID 34158625, 2021). "Furthermore, LyeTx I-b seems to be an efficient regulator of the 4T1 tumor microenvironment by modulating several cytokines, such as TGF-β, TNF-α, IL-1β, IL-6, and IL-10, in primary tumor and lung, spleen, and brain." (PMID 34572719, 2021). "This supports a promoting effect of the TNF-α/NF-κB/ROS axis on tumor progression." (PMID 33816268, 2021). "Our data provide a plausible explanation for why systemic administration of TNF failed as an effective therapy for malignancies: TNF must be delivered by tumor-reactive T cells during cognate interactions with the tumor targets in order to activate RIPK1-dependent cell death and tumor destruction." (PMID 34752416, 2021).
tumor (continued). "Our results revealed that BJJP remarkably reduced the expression of VEGFA and serum TNF-α, which may decrease damage done through tumor inflammation." (PMID 33762939, 2021). "In this regard, we have detected inflammatory factors including IL-1, IL-6, and TNF-α to help identify whether the increase of IL-5 and IFN-γ levels was caused by tumor progression or the concurrent inflammatory conditions." (PMID 34239620, 2021). "Furthermore, the function of T cells was tested through flow cytometry, and we found that PRMT5 deficiency in tumor cells enhanced IFN-γ, TNF-α and granzyme B secretion by CD8+ T cells." (PMID 34522232, 2021). "Accordingly, relieving the immunosuppression microenvironment leads higher levels of inflammatory factors (IFN‐γ and TNF‐α) in tumor tissues and stronger antitumor immune responses, which significantly enhanced the elimination efficiency of the established H22 tumors in mice." (PMID 33747739, 2021). "IL-8, IL-1β, MCP-1, RANTES, TNFα, and IL-6 also promote tumor cell migration and invasion." (PMID 34067089, 2021). "Additionally, macrophage-derived TNF-α can augment the PD-L1 expression in cancer cells, thus impeding T cells anti-tumor functions." (PMID 33514004, 2021). "The current research results showed that SPS-1 could activate macrophages with the increase of NO and TNF-α but it cannot directly induce tumor cell apoptosis." (PMID 34744741, 2021). "CD38 CAR-T cells could be activated effectively after stimulation with CD38-positive tumor cells and secrete cytokines such as IFN-γ and TNF-α to promote tumor cell apoptosis in in vitro experiments." (PMID 34513682, 2021). "At low levels, TNF-α may promote angiogenesis; however, at higher concentrations, it destroys the tumor vessels and increases the accumulation of drug in tumors." (PMID 33672813, 2021). "This sustained immune activation elicited by combination therapy was further supported by functional analysis demonstrating a significant increase in activated bifunctional CD8+ T cells producing both IFNγ and TNFα at day 25, which also correlated with tumor size reduction." (PMID 34446712, 2021). "In addition, TNF in the TIME can cause genetic damage and have other direct effects on malignant cells; for instance, TNF in the TIME can induce tumor cells to undergo the epithelial-mesenchymal transition (EMT), thus facilitating metastasis." (PMID 34867972, 2021). "While not evaluated in this study, evidence from other studies suggests that local tumor control is possibly mediated by IFNβ driven recruitment of cytotoxic CD8+ T-cells, TNF alpha mediated disruption of tumor microvasculature, and direct activation of apoptosis in cancer cells by STING signaling." (PMID 33659041, 2021). "Furthermore, it was found that the LLC tumor group showed high levels of TNF-α, IL-1β, and IL-6, and Alp reduced their serum concentrations in a dose-dependent manner." (PMID 34093209, 2021). "Additionally, recent studies have shown that TNFα also induces the expression of PD-L1 to promote tumor escape." (PMID 34445462, 2021). "We observed the expression of IL-2 and TNF-a in the tumor samples, demonstrating virus replication." (PMID 32920593, 2021). "In Drosophila, it was recently described that JAK/STAT and TNF-α/Egr signaling are elevated in cachectic muscle and promote tissue wasting in a model of scrib/RasV12 tumor-bearing larvae, which recapitulates the “high inflammation” that is a hallmark of human cancer cachexia." (PMID 34831432, 2021). "The tumor-associated angiogenesis process leads to the formation of irregular vessels, with more gaps, promoting an increase in factors such as nitric oxide, VEGF, tumor necrosis factor (TNF) and bradykinin, making it difficult for NPs to enter and act." (PMID 34452282, 2021).
tumor (continued). "CD4+ T cells primarily mediate anti-tumour immunity by providing help for CD8+ CTL and antibody responses, as well as via secretion of effector cytokines such as interferon-γ (IFNγ) and tumour necrosis factor-α (TNFα), and, under specific contexts, via direct cytotoxicity against tumour cells." (PMID 32457487, 2021). "Under the stimulation of IFN-γ, microbial stimulation (such as LPS), and cytokines (TNF, GM-CSF), macrophages often polarize to the M1 phenotype, with high bactericidal, bacteriostatic, pro-inflammatory and tumor cytotoxic activity, and the potential to kill tumor cells." (PMID 33935714, 2021). "Prolonged alcohol exposure activates monocytes and macrophages, resulting in an increased production of pro-inflammatory cytokines such as TNF, which could contribute to tumor initiation and progression." (PMID 34888239, 2021). "TNF-R2, on the other hand, can transform the tumor-suppressive TNF into the tumor promoter." (PMID 34630563, 2021). "Moreover, TNF‐α concentration in TTCS or tumor tissues were significantly increased when compared to those in NTCS or non‐tumor tissues." (PMID 34185422, 2021). "In addition, the expression of PD-L1 is also regulated by proinflammatory cytokines in the tumor microenvironment, such as tumor necrosis factor-α (TNF-α), type I and type II interferons, and VEGF, among which interferon-γ is the most potent." (PMID 34805266, 2021). "Hence, it is important to understand the TNF-α modulated mitochondrial proteome to understand the differential mitochondrial role in driving the tumor characteristic and heterogeneity." (PMID 33926547, 2021). "Studies found that TNF-α is closely related to the malignant behavior of the tumor." (PMID 34016788, 2021). "Furthermore, the NF‐κB activated by TNF further releases pro‐inflammatory and proangiogenic factors to promote tumour vessel formation and tumour cell survival." (PMID 33300633, 2021). "Additionally, GO-Y030-treated tumor models tended to have more IFN-γ and TNF-α production from CD8α+ cells in tumor-infiltrating lymphocytes." (PMID 34248973, 2021). "Growth factors, such as epidermal growth factor (EGF), platelet-derived growth factor (PDGF), pro-inflammatory cytokines, tumor necrosis factor (TNF), tumor promoters, bile acids and ultraviolet B irradiation, are involved in the stimulation of COX-2 expression." (PMID 34640461, 2021). "High levels of TNF-α generated a cytotoxic effect in tumor cells and inhibited tumor growth." (PMID 33408768, 2021). "Furthermore, TNF-α produced during early stages of inflammation has been described in the origin, development, survival and promotion of tumor growth in either CAC or CRC." (PMID 34681866, 2021). "Chronic inflammation is the key driver of the CAC; the RNA-seq transcriptome study demonstrated that MSCs reduce tumor initiation through immune responses, so we detected pro-inflammatory cytokines TNF-α, IL-1β, and IL-6 in serum to determine the systematic immune responses." (PMID 34150751, 2021). "The accumulated evidences indicated that M1 conditioned medium (M1 CM) could inhibit tumor growth via TNF-α, CXCL9, IFN-γ, or CCL3 in different types of cancers." (PMID 33175182, 2021). "IL-6, IL-1β, and TNF-α are 3 cytokines relevant to immunosuppression and tumor progression." (PMID 34422050, 2021). "Here, we demonstrated that both SEVs are also able to induce a significant upregulation of NF-kB at the protein level, leading to an increase in TNF-α and IL1β expressions; this contributes to the creation of an inflammatory microenvironment able to support and to enhance tumor progression." (PMID 34829995, 2021). "When macrophages are exposed to cytokines such as bacterial lipopolysaccharide (LPS), microbe-associated molecular patterns (MAMPs), IL12, TNF, interferon-γ (IFNG), or other Toll-like receptor (TLR) agonists, they will be in a pro-inflammatory and anti-tumor state, hence M1-like." (PMID 34447750, 2021).
tumor (continued). "Recruitment of MDSC in the TME aid in this suppression of TH immune cells, where TNF-α, IL-1, IL-6, colony stimulating factor 1 (CSF-1), IL-8, IL-10, and type I interferons can also play a role in the regulation of TH immune response to tumor cells." (PMID 34012451, 2021). "In addition, interleukin-6 (IL-6), interleukin-11 (IL-11), and tumor necrosis factor alpha (TNF-α) produced in tumor cells also enhance osteoclast formation and activation or osteoclast precursor activation." (PMID 33672879, 2021). "Some researchers have proposed that local enhancement of endogenous TNF-α activity can accelerate the death of tumor cells without the associated systemic toxicity." (PMID 34630563, 2021). "Inflammatory cells, such as neutrophils, promote adhesion and tumor seeding by secreting circulating growth factors; then, platelets can interact with tumor cells and activate several signaling pathways (TNF-⍺, NF-κβ, and TGF-β/Smad) that are related to the promotion of EMT and metastasis." (PMID 34204259, 2021). "In addition, metformin improves immune response by increasing CD8+ tumor-infiltrating lymphocytes and decreasing inflammatory chemokine production of IL-2, TNFα, and IFNγ." (PMID 34055551, 2021). "Another study confirmed these results by demonstrating an upregulation of lincRNA-p21 in TAMs, whereas knockdown facilitated macrophage polarization to M1 by upregulating TNF-α, IL-6, and iNOS, downregulating IL-10, IL-4, and Arg-1, and reducing tumor-cell proliferation and migration." (PMID 34439281, 2021). "Notably, combinatorial treatment with tamoxifen and TNFα or sh-NCOR1 decreased the tumor volumes more consistently than TNFα or sh-NCOR1 treatment alone." (PMID 34073371, 2021). "Interestingly, MITF expression can modify the inflammatory status of the tumor microenvironment by inhibiting c-Jun and subsequently decreasing TNFα." (PMID 34604096, 2021). "Further therapeutic strategy is genetic modification of MSC to overexpress specific immunomodulatory cytokines, suicide genes and other molecules that can effectively inhibit tumor progression, including IFNα, IFNβ and (TNF)-related apoptosis-inducing ligand (TRAIL)." (PMID 34095111, 2021). "Importantly, TNF-α secreted by TAMs leads to the activation of NF-κB in tumor cells, preventing tumor cell death and enhancing tumor cell invasion." (PMID 33968034, 2021). "TNF-α has both tumor-promoting and tumor-suppressing roles in the TME." (PMID 33986746, 2021). "For example, the absence of LAP would activate the STING signal pathway via the produced autoantigens (dsDNA) to induce pro-inflammatory gene expression (IL-6, TNF-α), polarizing TAMs into M1 macrophages and promoting the activation and differentiation of T cells to restrict tumor growth." (PMID 34956229, 2021). "In the present review, we describe recent advances in the development of novel soluble biological markers (e.g., circulating immune cells, TMB, circulating tumor cells, circulating tumor DNA, soluble factor PD-L1, tumor necrosis factor, etc.)for patients with NSCLC treated with immunotherapy." (PMID 34503087, 2021). "Moreover, we found an increased population of activated CD44+ T cells in tumor and TNF-α producing effector CD4+ and CD8+T cells in the spleen." (PMID 33499256, 2021). "In addition, macrophages can secrete cytokines such as IL-6 and TNF-α to kill tumor cells by binding to polysaccharides or glycoproteins through a variety of receptors." (PMID 34641277, 2021). "However, in early tumors, tumor-associated neutrophils (TAN) are more cytotoxic and produce higher levels of TNF-α, NO, and H2O2." (PMID 33946188, 2021). "Firstly, SMAC mimetics and OV in combination can sensitize tumor cells to TNFα-dependent killing." (PMID 34899741, 2021). "Tumor angiogenesis is strongly promoted by CAFs through the production of immunomodulatory and pro-angiogenic chemokines and cytokines like IL-4, IL-8, IL-6, TNF, CXCL12, TGFβ and VEGF." (PMID 33472580, 2021).
tumor (continued). "It has been proven that MUC-1-protein-functionalized GNPs serve as a powerful macrophage activator, promoting the release of TNF-α, IL-6, IL-10, and IL-12 on peritoneal macrophages, resulting in predominant M1 polarization, which showed a promising prospect as a tumor vaccine." (PMID 34572503, 2021). "In summary, TNFRSF9, TNF, and IFNG represent an efficient and effective surrogate combination for a much broader panel of functions associated to tumor-reactivity, and can potentially identify the majority of the tumor-specific reactive TIL repertoire in situ." (PMID 34707600, 2021). "Furthermore, a two-stage carcinogenesis experiment using TNF-α-knockout mice revealed the key role of TNF-α in tumor-promoting inflammation." (PMID 33804551, 2021). "This NF-κB/TNF-α positive feedback loop has been suggested to contribute to the aggressiveness of the tumor leading to the expression of several pro-survival genes, thereby further promoting tumor progression." (PMID 33816268, 2021). "During angiogenesis, multiple angiogenic activators such as VEGF, basic fibroblast growth factor (bFGF), angiogenin, transforming growth factor (TGF)-α, TGF-β, and tumor necrosis factor (TNF)-α become activated to promote the molecular signaling of tumor angiogenesis." (PMID 33805840, 2021). "Since the level of the mitochondrial mass is decreased in TNFα- tumor cells, we can also speculate, that there can be some increase of mitochondrial activity." (PMID 33957885, 2021). "TNF-α has been shown to suppress cellular responses to AhR activation and has been considered as an anti-tumor cytokine owing to its strong cytotoxic effects on some tumor cells in vitro." (PMID 33961948, 2021). "However, previous studies showed the presence of TNF-alpha in the vitreous humour of UM patients, where it correlates with tumour prominence and size." (PMID 34283046, 2021). "Meanwhile, IFN‐γ and TNF‐α have been revealed to be involved in the clearance of virus and tumours." (PMID 33733587, 2021). "Indeed, although considered to be an anti-tumor factor at high concentrations, TNFα exhibits a deleterious effect due to its ability to stimulate regulatory CD4 T cells." (PMID 33498483, 2021). "Notably, in the work summarized above, low doses of TNF that were tolerable for weeks were sufficient to upregulate tumor cell MHC-I and enhance ICI efficacy." (PMID 34277419, 2021). "TNF is known to induce direct killing on several tumor cell lines." (PMID 34576184, 2021). "Hence, PI3Kα pro‐metastatic action acts both via a direct actin cytoskeleton remodelling and FGFR‐induced tumour cell migration as well as via tumour‐extrinsic promotion of TNFα secretion by macrophages and subsequent further activation of migratory phenotype." (PMID 34033220, 2021). "To verify whether TNF-α has a direct contribution to the inhibition of tumor cell proliferation and migration, we neutralized the CM of 4 Gy irradiated MDA-MB-231 cells co-cultured with U937 (CM (IR+Mφ)) with anti-TNF-α antibody (αTNF)." (PMID 33867819, 2021). "Moreover, the tumor cell killing activity of the heat-inactivated supernatant was substantially restored by the addition of IFNγ and TNFα." (PMID 32666260, 2021). "However, depending on the cytokine milieu of tumour ME, MC can conversely release antitumorigenic molecules, such as TNF-α and IL-9." (PMID 34298847, 2021). "Furthermore, we discovered that there is significantly positive correlation between extent of VCAM1 staining (Low, Medium or High) and percentage of TNF-alpha expressing GAMs cells per mm2 tumor area (Spearman, R = 0.8, p = 2.738e-009)." (PMID 33853689, 2021). "After irradiating the tumor site with near-infrared (NIR) light, gold NPs could induce the expression of TNF-α and effectively kill the tumor cell." (PMID 34138211, 2021).